STAT3 (signal transducer and activator of transcription 3)
Diseases named in the same sentence as STAT3 in open-access papers (continued):
Sharing a sentence is not in itself a finding about the gene and the disease.
psoriasis (continued). "The phosphorylation of Signal Transducer and Activator of Transcription (STAT) is required for signal transmission, STAT-3 being particularly important in psoriasis." (PMID 30744173, 2019). "For instance, it antagonizes the activation of signal transducer and activator of transcription 3 (STAT3) and the subsequent production of IL-6, which is a major inflammatory molecule involved in psoriasis." (PMID 30918469, 2019). "STA-21, a promising STAT3 inhibitor that equally regulates Th17 and Treg cells, is known to prevent psoriasis and improve autoimmune inflammation." (PMID 30430364, 2019). "In the skin, STAT3 has a dual role in maintaining homeostasis and wound-healing as well as promoting carcinogenesis and psoriasis when aberrantly expressed." (PMID 31892232, 2019). "It has been shown that the mRNA expression of STAT3 in psoriasis patients with BSS was significantly higher than that in healthy people." (PMID 31781274, 2019). "Consistently, transgenic mice, in which keratinocytes express a constitutively active form of STAT3, develop psoriasis-like skin lesions." (PMID 31569642, 2019). "Many lines of evidence intimately link STAT3 aberrant activity with the development and progression of psoriasis, starting from the observation of high levels of activated STAT3 in the skin of psoriatic patients." (PMID 29316631, 2018). "As a central regulator of inflammatory and immune responses, the transcription factor STAT3 has recently emerged as a key player in the development and pathogenesis of psoriasis and psoriatic-like inflammatory conditions." (PMID 29316631, 2018). "The JAK/STAT3 dependent cytokine IL-23 is a fundamental mediator of psoriasis, since it stimulates Th17 cells to produce IL-17, which is another key molecule in psoriasis pathogenesis." (PMID 29316631, 2018). "Of note, STAT3 appears to be also required for the expansion and function of γδ T cells, which contribute to psoriasis pathogenesis by dermal production of IL-17." (PMID 29316631, 2018). "In this study, we demonstrated that topical application of PG102 ameliorates clinical symptoms of psoriasis by inhibition of STAT3-mediated proliferation of keratinocytes and neutrophil infiltration to skin." (PMID 30279326, 2018). "In psoriasis patients, the STAT3 protein is located in the cytoplasm and nuclei of the whole or middle layer of the epidermis, whereas STAT3 is only present in the cytoplasm of the epidermal basal layer in normal epidermis." (PMID 29292715, 2017). "K5-Stat3C transgenic mice that specifically express constitutively activated Stat3 in the epidermis develop psoriasis-like skin lesions, indicating that Stat3 activation is critical for psoriasis development." (PMID 28272440, 2017). "Interleukin-22 (IL-22) and the transcription factor Stat3 play pivotal roles in the pathogenesis of psoriasis." (PMID 28272440, 2017). "The prominent role of STAT3 in the pathogenesis of psoriasis is intriguing, i.p. as we also observe staining for P-STAT3 in keratinocytes in our mouse models." (PMID 29066712, 2017). "Clinically, Stat3 is a novel target involved in the development of psoriasis; Stat3 is constitutively active in psoriasis, and its expression is correlated with the severity of the disease." (PMID 26893174, 2016). "The present results also confirmed that consistent Stat3 activation was a crucial pathogenesis event of psoriasis because Stat3 was constitutively activated in psoriatic lesional skin." (PMID 26893174, 2016). "Our data provide direct experimental evidence of the possibility of targeting HO-1/Stat3 for psoriasis therapy." (PMID 26893174, 2016). "Stat3 acts as a positive regulator for the development of psoriasis; however, the molecular mechanism of Stat3 activation in keratinocytes is unclear." (PMID 26893174, 2016).
psoriasis (continued). "The IMQ-induced psoriatic mouse model and cultured keratinocytes were used to demonstrate the therapeutic effects of HO-1 on psoriasis, and the results suggest that the anti-psoriasis function of HO-1 was largely attributed to its effect on Stat3." (PMID 26893174, 2016). "We, and others have shown that IL-6 and its downstream targets (e.g. Stat3) are involved in the pathogenicity of IMQ-induced psoriasis-like skin disease and development of psoriatic lesions." (PMID 26999594, 2016). "Among the gene polymorphisms that have been linked to psoriasis are genes encodingIL23A,IL23R,STAT3,RUNX3, andTYK2." (PMID 27158469, 2016). "The current study supports the conclusion that keratin 16 and keratin 17 expression in keratinocytes were upregulated by Stat3-dependent mechanisms, accelerating the development of psoriasis." (PMID 26893174, 2016). "Genome-wide association studies (GWAS), for example, have identified variants near TF-encoding genes with significantly elevated frequency in psoriasis patients (e.g., ETS1, IRF4, KLF4, RUNX3, STAT3, STAT5A and STAT5B)." (PMID 25883770, 2015). "In K5.Stat3C mice, where keratinocytes express a constitutively active Stat3 and develop psoriasis-like skin lesions, Stat3 was targeted with a decoy oligonucleotide and after treatment psoriatic lesions were reversed." (PMID 26136626, 2015). "Several recently identified single-nucleotide polymorphisms (SNPs) that are linked to psoriasis susceptibility are found adjacent or in close proximity to genes associated with the innate immune response, such as IFIH1 (MDA5), NFKBIA, STAT3, and SOCS1." (PMID 25658361, 2015). "The key pathogenetic role of IL-6 signaling pathway in psoriasis is supported by evidence deriving from mouse models of psoriasis-like skin disease relying on constitutive activation of STAT3 in keratinocytes." (PMID 25126586, 2014). "Increased activation of STAT3 (pSTAT3) has been detected in lesional skin of psoriatic patients; several cytokines upregulated in psoriasis, including IL-6, IL-20, and IL-22, signal through STAT3 activation." (PMID 25126586, 2014). "Recently, risk susceptibility loci for Crohn's disease and psoriasis have been mapped at or near JAK2 and STAT3." (PMID 23372669, 2013). "IL-23 is also well known to be an important STAT3 cytokine related to skin disorders such as psoriasis." (PMID 22792286, 2012). "The transcription factor signal transducer and activator of transcription 3 (STAT3) is upregulated in psoriasis." (PMID 23133751, 2012). "NB-UVBtreatment clearly reduced markers of psoriasis activity such as epidermalphosphorylated STAT3, dendritic cell and neutrophilic granulocyte infiltratesand angiogenesis." (PMID 21611195, 2011). "STAT3 is phosphorylated in psoriasis, as well as in a wound-response type model of psoriasis induced by serum response factor-deficiency." (PMID 20300524, 2010). "Second, PTK6 kinase, which also phosphorylates STAT3, is the most highly upregulated kinase in psoriasis and PPARβ/δ mice." (PMID 20300524, 2010). "SOCS-3 negatively regulates the activation of the transcription factor signal transducer and activator of transcription 3 (STAT-3), which is indeed overly active in psoriasis and implicated in cytokine signaling." (PMID 20594301, 2010). "Second, Wnt5a is itself strongly induced by STAT3, thereby acting as a potential effector molecule for the psoriasis-like skin disease seen in STAT3-overexpressing transgenic mice." (PMID 19399181, 2009). "Notably, IMQ also considerably enhanced phosphorylation of STAT3, a key player in the development and pathogenesis of psoriasis and psoriatic-like inflammatory conditions, which was significantly inhibited by CS1, but not Tapinarof treatment." (PMID 40807399, 2025). "This raises the possibility that OCFAs may exert context-specific effects on psoriasis by modulating STAT3 or other cytokine signaling pathways." (PMID 40356914, 2025).
psoriasis (continued). "Further studies are needed to investigate whether methoxyflavones modulate upstream signaling pathways, such as NF-κB, STAT3, or mitogen-activated protein kinases (MAPKs), which are well-established drivers of inflammation and immune activation in psoriasis." (PMID 40508056, 2025). "Moreover, elevated STAT3 levels have been detected in rosacea and psoriasis, and JAK inhibitors have been shown to effectively alleviate clinical symptoms." (PMID 40346694, 2025). "Moreover, the signal transducer and activator of transcription 3 (STAT3) participated deeply in regulating the pathogenesis of psoriasis and can be targeted to inhibit its development." (PMID 40299379, 2025). "However, the precise role of the S1P/S1PR pathway in psoriasis keratinocytes and its potential contribution to the sustained STAT3 activation observed in this disease remain largely unexplored." (PMID 39833165, 2025). "However, to generate a psoriasis model that mimics in vivo skin and especially skin immunity more closely, we integrated the STAT3 overexpressing keratinocytes in our established immune-cell supplemented full-thickness skin model." (PMID 40678130, 2025). "Collectively, the findings indicate that UC-MSCs-EVs attenuate psoriasis-like inflammation through convergent inhibition of DC-derived IL-23 and keratinocyte STAT3 signaling, supporting their development as a cell-free immunomodulatory therapy for chronic inflammatory skin disease." (PMID 41226338, 2025). "However, persistent STAT3 activation during skin inflammation is a distinguishing characteristic of psoriasis in patients and in imiquimod (IMQ)-induced psoriasiform dermatitis mouse model." (PMID 39833165, 2025). "In addition to in vitro, psoriasis symptoms, keratinocyte proliferation, and expressions of NF-κB and p-STAT3 are reduced by treatment with TGN in the IMQ-induced psoriasis mouse model." (PMID 40298779, 2025). "Nevertheless, our integrated network pharmacology and untargeted metabolomics approach identified high-confidence targets (e.g., STAT3, GSH metabolism) associated with inflammatory skin diseases such as psoriasis, supporting the translational potential of β-Acetoxyisovalerylalkannin." (PMID 41011121, 2025). "Our study suggests that disrupting the S1PR3–STAT3 feedback loop may offer a novel strategy for treating psoriasis and potentially other chronic inflammatory diseases driven by persistent STAT3 activation." (PMID 39833165, 2025). "The increased expression of S1PR3 was the major cause of persistent STAT3 activation in psoriasis keratinocytes, suggesting that S1PR3 and STAT3 are involved in interactions between sphingolipid metabolites and abnormal proliferation in psoriasis patients." (PMID 39833165, 2025). "Mechanistically, IL-33 may impair Th17 differentiation via suppression of RORγt (RORC) and STAT3 signalling while promoting Treg expansion, rebalancing immune homeostasis in psoriasis." (PMID 40681996, 2025). "Thus, in K5.STAT3C mice, the abundance and hyperactivation of STAT3 in psoriasis was successfully used to recapitulate some psoriatic characteristics in murine models, confirming STAT3 as a possible target for psoriasis treatment." (PMID 40678130, 2025). "Targeting the S1P/S1PR3/STAT3 axis might serve as a potential therapeutic strategy for patients with psoriasis." (PMID 39833165, 2025). "In addition, MSCs suppress Th17 cell differentiation through IFN-γ-mediated STAT1 activation, which upregulates SOCS3 and inhibits STAT3 signaling, ultimately exerting immunomodulatory effects in autoimmune diseases, including psoriasis." (PMID 40906403, 2025). "Porcine models of psoriasis are characterised by psoriasis‐related manifestations: erythema, swelling, the presence of silvery lesions, increased expression levels of STAT3, VEGF and T helper 17 cells; parakeratosis and hyperkeratinisation within the epidermis." (PMID 40400213, 2025).
psoriasis (continued). "Key nodes such as STAT3, TRAF6, and PTEN emerged, showing convergence on inflammatory signaling, keratinocyte proliferation, and immune regulation, which represent core pathogenic mechanisms in psoriasis." (PMID 41458345, 2025). "Immunohistochemical, western blot, and multiplex analysis showed that the TLR activation induced the expression of psoriasis associated markers like S100A7, p-STAT3, CXCL-1, IL-8, IL-1α, S100A9, and IL-23 in the wild type but not in the TLR KO epidermis models." (PMID 40995100, 2025). "PSVII could modulate pyroptotic cell death in psoriatic cells by targeting the STAT3/NFκB signaling cascade, leading to anti-inflammatory and anti-proliferative effects, and thereby ameliorating psoriasis symptoms." (PMID 40405066, 2025). "Psoriasis, a multifactorial inflammatory condition, has prompted a growing interest in RNA-based therapies, particularly siRNA and miRNA approaches targeting STAT3, keratin 17, and TNF-α pathways, which aim to normalize keratinocyte behavior, suppress inflammation, and modulate angiogenesis." (PMID 40724842, 2025). "The skin of individuals with psoriasis exhibits elevated STAT3 expression." (PMID 40166646, 2025). "In addition, the persistent activation of STAT3 in psoriasis was attributed to elevated S1PR3 in the epidermal skin, resulting in positive feedback between S1PR3 and STAT3." (PMID 39833165, 2025). "This analysis revealed that both STAT3 and Caspase-1 are significantly upregulated in psoriasis." (PMID 40405066, 2025). "Thus, STAT3 is considered to be a potential target for the therapy of psoriasis and STAT3 inhibitors are investigated as a treatment option." (PMID 40678130, 2025). "In this study, we established STAT3 overexpressing human keratinocytes and combined the cells with our epidermis and immune cell supplemented full-thickness skin model to generate a novel in vitro psoriasis model." (PMID 40678130, 2025). "Both epidermal and full-thickness skin models set up from STAT3 overexpressing keratinocytes showed a stronger psoriasis-like phenotype upon pro-inflammatory stimuli such as treatment with cytokines or integration of T cells compared to skin models set-up from the wild-type keratinocyte cell line." (PMID 40678130, 2025). "Moreover, STAT3, together with NF-κB and AP-1 pathways, is involved in the production of pro-inflammatory cytokines, which play a key role in psoriasis, as well as in other inflammatory conditions, such as atopic dermatitis." (PMID 40508214, 2025). "We identified 34 housekeeping genes associated with psoriasis and observed that the co-expression relationships between six genes (APOL2, DCUN1D3, UBE2F, HIGD1A, PPIF, and STAT3) and known psoriasis-related genes differed significantly between diseased and healthy individuals." (PMID 40959079, 2025). "Rosmarinic acid attenuated imiquimod (IMQ)-induced psoriasis-like inflammation in mice by decreasing IL-23 expression, inhibiting Th17-dominated inflammation, downregulating the Janus kinase 2 (Jak2)/STAT3 signaling pathway, and inhibiting keratinocyte hyperproliferation in vivo and in vitro." (PMID 38542838, 2024). "Previous reports showed that STAT3 hyperactivation regulates inflammatory pathways that play a crucial role in the onset of psoriasis, and inhibiting STAT3 can effectively alleviate psoriasis symptoms by reducing Th17 cell differentiation and inflammatory cytokine signaling." (PMID 39590306, 2024). "Centella asiatica blocked the JAK/STAT3 signaling, resulting in alleviating psoriasis." (PMID 39167035, 2024). "Curcumol may reduce psoriasis-like inflammation via inhibiting JAK1/STAT3 signaling in keratinocytes." (PMID 38914581, 2024). "Tanshinone components could alleviate RA, SLE, IBD, and Psoriasis by regulating the STAT3 signaling pathway." (PMID 38542838, 2024).
psoriasis (continued). "Interestingly, psoriasis is driven by the activation of many signaling pathways and transcription factors, including STAT3, C/EBPβ, and AP-1, triggered by damage- or inflammation-associated molecules released from dying keratinocytes and invading immune cells." (PMID 39358322, 2024). "In addition, visfatin can acts on keratinocytes to amplify the inflammatory state through the NF-κB and STAT3 signaling pathways as well as upregulation of several chemokines, thereby increasing the severity of psoriasis." (PMID 38683749, 2024). "STAT3 has a multifaceted role in psoriasis and influences several cell types." (PMID 38303723, 2024). "STAT3 is a crucial signaling molecule in psoriasis development." (PMID 38892253, 2024). "IL-6 and IL-22 work synergistically with IL-17A as potent STAT3 activators in psoriasis." (PMID 38892253, 2024). "Rutin could lighten M5‐induced inflammation and abnormal differentiation in HaCaT cells by mediating the JAK2/STAT3 signaling, which offers evidence to bolster the potential of Rutin as a drug for managing psoriasis." (PMID 39167035, 2024). "Additionally, a non-canonical pathway characterized by phosphotyrosine-independent massive STAT3 activation contributes to IL-22 functions and is implicated in imiquimod (IMQ)-induced psoriasis in mice." (PMID 38892253, 2024). "Researchers have identified STAT3, TYK2, IL23A, and IL23R as susceptibility factors for psoriasis." (PMID 39296901, 2024). "Adverse events, such as cytopenias in two patients (patients 14 and 34), psoriasis (patient 12), and APS-associated stroke (patient 40), could represent STAT3-GOF-related manifestations and rather reflect the incomplete efficacy of JAKi treatment." (PMID 39247195, 2024). "On the contrary, TG3 is upregulated in psoriasis and acts as a protective factor by inhibiting the activation of nuclear factor kappa-B (NF-κB) through the phosphorylated STAT3-ten-eleven translocase 3 (p-STAT3-TET3) pathway, which thereby reduces skin inflammation." (PMID 38606161, 2024). "Therefore, we subsequently examined the activation of STAT3 and NF-κB p65 in keratinocytes in psoriasis-like conditions." (PMID 39090602, 2024). "STAT3 is a key player in psoriasis pathogenesis and psoriasiform inflammation." (PMID 39167035, 2024). "STAT3 is also upregulated in both PsA and psoriasis patients." (PMID 37894979, 2023). "This study demonstrated that BAC might act as an inhibitor of STAT3 in psoriasis to inhibit STAT3 phosphorylation in TNF-α-induced HaCaT cells to regulate the proliferation and expression of inflammatory cytokines." (PMID 37298949, 2023). "Meanwhile, STAT1 and STAT3 have been shown to be involved in the cytokine–cytokine receptor interaction pathway, and indeed, these targets are involved in suppressing the pathology of immune-mediated inflammation in psoriasis." (PMID 37631075, 2023). "Also, animal models of psoriasis demonstrated that inhibition of the JAK/STAT3 pathway promoted macrophage polarization, which upregulated a profibrotic factor and, thereby, favorably alleviated tissue inflammation." (PMID 37628972, 2023). "In addition, SIRT1 reduced lesion severity in an Aldara-induced psoriasis model by decreasing STAT3 activation." (PMID 37445960, 2023). "Dysfunctional Tregs in peripheral blood of patients with psoriasis have been reported showing that they have a phosphorylation and an aberrant activation of STAT3, which is due to the effects of pro-inflammatory cytokines, not only IL-6, but also IL-21 and IL-23." (PMID 36901778, 2023). "miR-125a-5p may have therapeutic potential in psoriasis by restoring the suppressive function of Tregs on Th17 cells through targeting STAT3, and on Th1 cells indirectly through targeting ETS-1 and IFN-γ." (PMID 37773129, 2023). "In addition, GA was reported to ameliorate psoriasis symptoms by inhibiting inflammatory cytokines and the STAT3/mTOR signaling pathway." (PMID 37643205, 2023).